SULT1A1 (sulfotransferase family 1A member 1)
Description:
Sulfotransferase that utilizes 3'-phospho-5'-adenylyl sulfate (PAPS) as sulfonate donor to catalyze the sulfate conjugation of a wide variety of acceptor molecules bearing a hydroxyl or an amine group. Sulfonation increases the water solubility of most compounds, and therefore their renal excretion, but it can also result in bioactivation to form active metabolites. Displays broad substrate specificity for small phenolic compounds. Plays an important role in the sulfonation of endogenous molecules such as steroid hormones. Mediates the sulfate conjugation of a variety of xenobiotics, including the drugs acetaminophen and minoxidil (By similarity). Mediates also the metabolic activation of carcinogenic N-hydroxyarylamines leading to highly reactive intermediates capable of forming DNA adducts, potentially resulting in mutagenesis. May play a role in gut microbiota-host metabolic interaction. O-sulfonates 4-ethylphenol (4-EP), a dietary tyrosine-derived metabolite produced by gut bacteria. The product 4-EPS crosses the blood-brain barrier and may negatively regulate oligodendrocyte maturation and myelination, affecting the functional connectivity of different brain regions associated with the limbic system. Catalyzes the sulfate conjugation of dopamine. Catalyzes the sulfation of T4 (L-thyroxine/3,5,3',5'-tetraiodothyronine), T3 (3,5,3'-triiodothyronine), rT3 (3,3',5'-triiodothyronine) and 3,3'-T2 (3,3'-diiodothyronine), with a substrate preference of 3,3'-T2 > rT3 > T3 > T4.
Synonyms: ST1A1; P-PST 1; Ts-PST; STP; STP1; P-PST; HAST1/HAST2; PST; ST1A3; TSPST1
Tractability: Small molecule: a structure with a bound ligand is known; a high-quality ligand is known; it has a high-quality binding pocket. PROTAC: ubiquitination databases record sites on it; its protein half-life has been measured; a small molecule that binds it is known.
Target class: Enzyme; Transferase
Safety:
Unwanted effects reported when the protein is acted on. In parentheses: how it was acted on, where the effect was seen, and who reports it.
endometrial neoplasms (source: ClinPGx)
Gene: Protein-coding gene on chromosome 16 (28,605,008 to 28,612,503, reverse strand). Ensembl gene ENSG00000196502.
Subcellular location: Cytoplasm
Pathways (Reactome):
Drug ADME: Paracetamol ADME
Metabolism: Cytosolic sulfonation of small molecules
Gene Ontology:
Molecular function: 3'-phosphoadenosine 5'-phosphosulfate binding; aryl sulfotransferase activity; flavonol 3-sulfotransferase activity; protein binding; steroid sulfotransferase activity; sulfotransferase activity
Biological process: 3'-phosphoadenosine 5'-phosphosulfate metabolic process; dopamine catabolic process; estrogen metabolic process; ethanol catabolic process; flavonoid metabolic process; sulfation; thyroid hormone metabolic process; xenobiotic metabolic process; amine metabolic process; sulfur compound metabolic process
Cellular component: cytoplasm; cytosol
Genetic constraint (gnomAD): Loss-of-function variants: 35 observed, 34.9 expected, observed/expected ratio (o/e) 1, 90% interval 0.76 to 1.33. The upper end of that interval is the gene's LOEUF score, 1.33, which puts it in group 5 of 6, group 1 being the genes least tolerant of losing a copy. Missense variants: 309 observed, 347.58 expected, observed/expected ratio (o/e) 0.89, 90% interval 0.81 to 0.98. Synonymous variants: 119 observed, 131.35 expected, observed/expected ratio (o/e) 0.91, 90% interval 0.78 to 1.05.
Homologues: Orthologues: tropical clawed frog sult1b1 (50% identical), zebrafish sult1st3 (49% identical), zebrafish sult1st1 (49% identical), zebrafish sult1st2 (49% identical), zebrafish sult1st7 (49% identical), zebrafish sult1st9 (48% identical), zebrafish sult1st4 (47% identical), tropical clawed frog sult5a1 (40% identical), zebrafish sult5a1 (39% identical), zebrafish sult2st1 (38% identical), zebrafish sult2st3 (38% identical), zebrafish sult2st2 (37% identical), and 6 more. Paralogues in human: SULT1A2 (96% identical), SULT1A3 (93% identical), SULT1A4 (93% identical), SULT1B1 (54% identical), SULT1C4 (54% identical), SULT1C2 (51% identical), SULT1E1 (50% identical), SULT1C3 (49% identical), SULT2B1 (36% identical), SULT2A1 (35% identical), SULT4A1 (34% identical), SULT6B1 (31% identical).
Diseases named in the same sentence as SULT1A1 in open-access papers:
SULT1A1 is named in the same sentence as 104 diseases in open-access papers, as found by Europe PMC text mining. Sharing a sentence is not in itself a finding about the gene and the disease. The quoted sentences say what the papers report.
breast carcinoma (38 papers, 2005 to 2024). "Here we show that functional analysis of a candidate modifier gene using a model cell line is able to provide additional evidence that SULT1A1 deletions lead to reduced risk of breast cancer in BRCA1 pathogenic variant carriers." (PMID 36203093, 2022). "CNV deletions overlapping the lead candidate modifier SULT1A1 showed decreased breast cancer risk in BRCA1 pathogenic variant carriers." (PMID 36203093, 2022). "A similar relationship between CYP1A1 and SULT1A1 activity and reduced breast cancer risk has been demonstrated previously." (PMID 36203093, 2022). "The risk of germline copy number variants (CNVs) in BRCA1 and BRCA2 pathogenic variant carriers in breast cancer is assessed, with CNVs overlapping SULT1A1 decreasing breast cancer risk in BRCA1 carriers." (PMID 36203093, 2022). "In contrast, deletions overlapping SULT1A1 suggested a decreased breast cancer risk (HR = 0.73, 95% CI 0.59-0.91) in BRCA1 pathogenic variant carriers." (PMID 36203093, 2022). "In this study, univariate logistic regression analysis showed that CYP1A1, CYP1B1, and SULT1A1 gene polymorphisms are closely related to the occurrence of breast cancer." (PMID 33632172, 2021). "Previous clinical studies addressed the role of polymorphism in SULT1A1 in the survival of breast cancer patients." (PMID 32727562, 2020). "For instance, SULT1A1 catalyzes the sulfonation of a variety of small phenolic compounds including estrogen and is known to be associated with breast cancer risks." (PMID 27322429, 2016). "Polymorphisms in SULT1A1 are known to exist and one particular variant SULT1A1*2 (where Arg at codon 213 is substituted with His) has been seen in some breast cancer patients." (PMID 27322429, 2016). "Several studies have been performed to determine the association between SULT1A1 polymorphic alleles in blood cells and the risk of breast cancer, lung cancer, colorectal cancer, bladder cancer, and brain tumors, but the results have been inconsistent." (PMID 25514600, 2015). "And after removing this study, the significant association between SULT1A1 Arg213His and breast cancer risk became null." (PMID 25225888, 2014). "SULT1A1 Arg213His didn't show any association with breast cancer, but the possible risk in Asian population needs further investigation." (PMID 25225888, 2014). "In this prospective study, we observed a previously unreported association between the SULT1A1 rs9282861 genotype and OS of breast cancer patients treated with adjuvant chemotherapy or TAM." (PMID 22708928, 2012). "In summary, breast cancer patients with the SULT1A1 rs9282861 homozygous variant AA genotype and treated with either adjuvant TAM or chemotherapy had statistically significantly better OS compared with the carriers of other rs9282861 genotypes." (PMID 22708928, 2012). "The risk (odds ratio, OR) was used to estimate the association between SULT1A1 polymorphism and breast cancer risk." (PMID 20663177, 2010). "In the Yang's research, a possible association between SULT1A1 and breast cancer risk was also suggested for postmenopausal women." (PMID 20663177, 2010). "We performed a meta-analysis including ethnic subgroup and menopausal statue subgroup to investigate the association of SULT1A1 Arg213His polymorphism with breast cancer." (PMID 20663177, 2010). "Another important aspect that has emerged from the meta-analysis is the difference in the risk of breast cancer conferred by SULT1A1*2 variant to Asian women compared with Caucasian women." (PMID 18854828, 2008). "The low-activity SULT1A1*2 allele was linked to increased rates of mortality in breast cancer patients treated with TAM." (PMID 16884532, 2006). "Saintot and coworkers recently reported a positive interaction between smoking and the variant allele for SULT1A1 with respect to breast cancer risk in a case-only study." (PMID 15743503, 2005).
breast carcinoma (continued). "Multivariate logistic regression analysis was used to estimate breast cancer risk associated with the SULT1A1 Arg213His polymorphism alone and in combination with NAT2 genotype in relation to smoking." (PMID 15743503, 2005). "Two previous studies reported an increased risk for breast cancer associated with the SULT1A1*2 allele per se." (PMID 15743503, 2005). "Two additional studies have suggested a link between the low-activity allele (SULT1A1*2) and increased breast cancer risk." (PMID 16280036, 2005). "Characterising pathogenic variant type in BRCA1, and future screening for deletions overlapping SULT1A1, may produce variables to be incorporated with other modifying factors to develop a more comprehensive model of breast cancer risk." (PMID 36203093, 2022). "However, carrying the CYP1A1*2 C allele in combination with a SULT1A1*2 allele was strongly protective against developing breast cancer (OR = 0.14, 95%CI = 0.04–0.56) compared with women carrying only the CYP1A1*2 C allele." (PMID 36203093, 2022). "If verified, future therapeutic intervention studies targeting SULT1A1 in BRCA1 pathogenic variant carriers may lead to new medical options for reducing breast cancer risk." (PMID 36203093, 2022). "The mechanism by which CNV deletions overlapping SULT1A1 were associated with lower BRCA1-associated breast cancer risk may be linked to the production of potentially toxic catechol oestrogens by the Cytochromes P450 (CYP) enzymes." (PMID 36203093, 2022). "Finally, we showed that increased expression of the human enzymes that form IS (Cyp2E1, Sult1A1, and Sult1A2) is associated with better survival in breast cancer, an effect that is lost in triple negative cases." (PMID 33050543, 2020). "Alternative explanations may involve the role of genetic variations in SULT1A1 in breast cancer risk or in endogenous estrogen metabolism." (PMID 30120701, 2018). "Nevertheless, the more active allele of SULT1A1 has been associated with better survival outcome in breast cancer patients treated with tamoxifen, possibly because the SULT1A1-mediated biotransformation of 4-hydroxytamoxifen potentiates the efficacy of tamoxifen therapy." (PMID 25514600, 2015). "In addition to germline SNPs of tamoxifen-metabolizing genes, such as CYP19, CPY2D6, and SULT1A1, SNPs identified in genomewide association studies (GWAS) have been found to be associated with breast cancer risk." (PMID 24324964, 2013). "Our results clearly indicate that there may be an association between the SULT1A1 rs9292861 genotype and the survival of breast cancer patients, but further studies are warranted due to a relatively small sample size." (PMID 22708928, 2012). "The aim of this study was to determine whether the SULT1A1 rs9282861 genotype is associated with clinical outcome of patients diagnosed with early breast cancer and treated with either adjuvant TAM or chemotherapy." (PMID 22708928, 2012). "Inasmuch, an association between the rs9282861 homozygous variant AA genotype of sulfotransferase 1A1 (SULT1A1, involved in detoxification of 4-hydroxytamoxifen), and overall long-term survival of breast cancer patients treated with adjuvant tamoxifen, has been described." (PMID 23344024, 2012). "Previous clinical studies suggest that the SULT1A1 rs9282861 polymorphism may influence the survival of breast cancer patients treated with TAM in the adjuvant setting." (PMID 22708928, 2012). "SULT1A1*2 isoform is associated with increased risks of lung, stomach cancer, urothelial cancer, and breast cancer." (PMID 23264952, 2012). "Results on association of SULT1A1 Arg213His and risk of cancer are inconsistent, from null association with risk of colorectal cancer and prostate cancer to increase in risk of breast cancer associated with His213 allele." (PMID 22206016, 2011). "Another reason may be that SULT1A1 polymorphism has relation to breast cancer in part of the women and the whole population analysis may weaken this relationship." (PMID 20663177, 2010).
breast carcinoma (continued). "We concluded that the polymorphism of SULT1A1 Arg213His might be one of the high risk factors for breast cancer in Asian women and in postmenopausal women for all races." (PMID 20663177, 2010). "We next tested the hypothesis that MCF-7 breast carcinoma cells that were stably transfected with the SULT1A1*2 (low-activity) allele would proliferate faster in response to E2 exposure than cells expressing the SULT1A1*1 (high-activity) allele." (PMID 16280036, 2005). "However, our findings are consistent with Seth and colleagues, who also reported an association between SULT1A1*1 genotypes (homozygous or heterozygous) and early age of breast cancer onset." (PMID 16280036, 2005). "Several epidemiological studies have evaluated whether the SULT1A1 genotype is associated with altered risk for breast cancer." (PMID 16280036, 2005). "Thus far, three case–control studies that investigated the association between SULT1A1 genotype and breast cancer risk have been reported." (PMID 15743503, 2005). "Additional investigation of a common SULT1A1 genetic polymorphism associated with reduced enzyme activity and stability might therefore provide deeper insight into the modification of breast cancer susceptibility." (PMID 15743503, 2005). "In combination with NAT2 fast acetylator status, however, the SULT1A1*1/*1 genotype might increase breast cancer risk in women exposed to tobacco smoke." (PMID 15743503, 2005). "SULT1A1*2 (213His) allele has been associated with an increased risk of prostate cancer (OR = 1.60, 95% CI = 0.46–5.62), stomach cancer (OR = 3.32; 95% CI = 1.17–9.45), urothelial cancer (OR = 2.18, 95% CI = 1.28–3.69), and breast cancer (OR = 1.12, 95% CI = 1.02–1.24)." (PMID 23264952, 2012). "Multiple factors may act on the breast cancer risk among premenopausal women, but our analysis supported that the polymorphism of SULT1A1 may have significant effects on the relationship between breast cancer risk and SULT1A1 Arg213His polymorphism among the postmenopausal women." (PMID 20663177, 2010). "Polymorphism of the SULT1A1 may be closely associated with breast cancer." (PMID 20663177, 2010). "Because sulfotransferase (SULT)1A1 (encoded by SULT1A1) is also involved in the metabolism of pro-carcinogens from tobacco smoke, the additional investigation of a common polymorphism in the SULT1A1 gene might provide deeper insight into the modification of susceptibility to breast cancer." (PMID 15743503, 2005). "The potency and selectivity of these compounds in breast cancers is determined by their chemical composition as well as the overexpression of AhR and SULT1A1 proteins, with the latter presenting as a potential clinical biomarker for targeted therapy." (PMID 38974991, 2024). "We applied in silico and in vitro analyses to characterise a novel risk association between deletions overlapping SULT1A1 (OMIM 171150) and decreased breast cancer risk for BRCA1 pathogenic variant carriers." (PMID 36203093, 2022). "As deletions overlapping SULT1A1 were suggested to decrease breast cancer risk in BRCA1 pathogenic variant carriers, the relative expression of BRCA1 was quantified to assess if the SULT1A1 knockdown affected its regulation." (PMID 36203093, 2022). "In our study, CNV deletions overlapping SULT1A1 were identified in 1.7% of BRCA1 pathogenic variant carriers and they suggested a decreased breast cancer HR (HR = 0.73, 95%CI = 0.59–0.91, p = 9.1 × 10−3)." (PMID 36203093, 2022). "The association between other metabolizing enzymes such as CYP2D6 and SULT1A1 and the clinical response toward tamoxifen therapy in breast cancer patients have been also evaluated in several reports." (PMID 33503040, 2021). "Our ex vivo experiments using breast cancer samples demonstrated the efficiency of the combination of TMX with SULT1A1-dependent compounds, both in TMX-sensitive and TMX-resistant patients." (PMID 32727562, 2020).